STAT3 (signal transducer and activator of transcription 3)
Diseases named in the same sentence as STAT3 in open-access papers (continued):
Sharing a sentence is not in itself a finding about the gene and the disease.
liver cancer (continued). "TM4SF5 interacts with IL6R, leading to STAT3 activation independent of IL6 in hepatic cancer cells." (PMID 34921636, 2021). "In liver cancer treated with Newcastle disease virus (NDV), DCA significantly reduced the release of lactate in cancer cells, activation of signal transducer and activator of transcription 3 (STAT3), up-regulation of indoleamine 2,3-dioxygenase 1 (IDO1), and infiltration of MDSCs." (PMID 33027968, 2020). "IL-6, STAT3, TNF-α and NF-κB are reported to play a central role in inflammation and control the expression of an array of growth factors and cytokines that may involve in hepatic cancer development." (PMID 27760163, 2016). "Furthermore, STAT3 decoy ODN may reduce liver fibrosis and inflammation by inhibiting genes that increase liver fibrosis and promoting those that suppress liver fibrosis in hepatic cancer cells." (PMID 38338338, 2024). "At the same time, ATF4 and STAT3 inhibitors may have further applications in sorafenib-resistant liver cancer patients, and understanding the role of ATF4/STAT3 molecular pathways in HCC progression will contribute to the development of potential drugs for targeted treatment of liver cancer." (PMID 37326750, 2023). "Thus, our data in liver cancer cell lines are in line with previous studies in fibroblasts and ma-crophages whereby a disbalance between STAT1 and STAT3 may lead to the activation of IFN-γ/STAT1 target genes in a proinflammatory IL-6-containing tumor microenvironment." (PMID 35267462, 2022). "In liver cancer stem cells, Shh/Gli‐regulated cell functions were also found to be mediated by activation of the IL‐6/STAT3 pathway, but whether there is a similar direct effect of Shh‐blockade on IL‐6‐mediated STAT3 signaling was not reported." (PMID 34482626, 2022). "In the absence of the STAT3 inhibitor AG490, leptin-induced malignant behaviors were notably restrained, further confirming the powerful carcinogenic effect of leptin in liver cancer." (PMID 38273295, 2024). "Cryptotanshinone (CT), a STAT3 inhibitor, has exhibited certain anti-tumor potency; however, the use of CT enhanced ATO for treating liver cancer has not been reported." (PMID 28187727, 2017). "Our results showed that Raloxifene inhibited STAT3 phosphorylation induced by IL-6, but not by LIF in Hep-3B liver cancer cells." (PMID 28430601, 2017). "We were not able to detect JAK2 phosphorylation in these liver cancer cell lines and in SNU387 cell line, the phosphorylation of STAT3 (Ser727) could not be detected." (PMID 20712901, 2010). "However, in liver cancer, we found that PHKB may be independent of glycogen metabolism, but be related to p-AKT and p-STAT3 signaling pathway." (PMID 31754332, 2019).
cervical carcinoma (279 papers, 2007 to 2025). A carcinoma arising from either the exocervical squamous epithelium or the endocervical glandular epithelium. "A substantial body of literature indicates a strong association between the malignant phenotype of cervical cancer cells, including cancer stem cells, and the altered expression of STAT3 and NANOG." (PMID 40729003, 2025). "This study explores the interaction between immune and cancer cells in the tumor microenvironment (TME) of cervical carcinoma (CC), with emphasis on tumor‐associated macrophages (M2‐TAMs) and the STAT3‐NF‐κB signaling pathway." (PMID 41263059, 2025). "The activation of AP-1, NF-κB, and STAT3 transcription factors is known to be associated with proliferation and metastasis in human cervical cancer, primarily through the regulation of genes involved in cell survival, proliferation, and metastasis." (PMID 39273231, 2024). "Activation of the STAT3/IRF1 pathway increases the susceptibility of cervical cancer cells to chemical treatments." (PMID 38789431, 2024). "Similar properties of CucD have also been reported in cervical cancer cells and were associated with the inhibition of STAT3 activation." (PMID 39770403, 2024). "Constitutive STAT3 activation has been associated with various human cancers and has indicated poor prognosis, including in cervical cancer cells." (PMID 39273231, 2024). "Further keyword analysis showed that STAT3 and NF-κB are associated with cell death, inflammation, and tumor progression in cervical cancer." (PMID 38065854, 2023). "Chen found that ADAR1 edits multiple sites in the YXXQ motif of BLCAP (a tumor suppressor for bladder cancer), causing it to lose its inhibition of STAT3 activation, thereby promoting tumorigenesis in cervical cancer (CC)." (PMID 36895481, 2023). "In cervical cancer, the presence and activity of STAT3 is associated with the malignancy of cervical lesions." (PMID 35163748, 2022). "Inhibition of STAT3 signaling in tumor cells increases the apoptotic rate, and loss of active STAT3 has a significant impact on both cervical cancer cell proliferation and survival." (PMID 34975517, 2021). "Previously, the interaction between miR-411 and STAT3 has been demonstrated to be the mechanism underlying the tumor suppressor role of miR-411 in cervical cancer." (PMID 34606414, 2021). "Activation of IL-6/STAT3 signalling was observed in mice implanted with cervical cancer cells containing high-risk HPV E6." (PMID 33076322, 2020). "The autocrine and paracrine actions of IL-6 are essential for STAT3 activation in HPV positive cervical cancers and loss of the pathway results in increased cancer cell death and a reduction in proliferation." (PMID 31226168, 2019). "Loss of active STAT3 had a significant impact on both cervical cancer cell proliferation and survival." (PMID 31226168, 2019). "In cervical tumorigenesis, the activated IL-6 and STAT-3 induced senescence of fibroblasts in high-risk Human Papilloma Virus-infected cervical cancer." (PMID 29360827, 2018). "Constitutively-activated STAT3 is often detected in cervical carcinoma, which is associated with tumorigenesis, cancer progression and poor prognosis." (PMID 29416779, 2018). "It is already known that the cancer-associated fibroblast senescence induced by high-risk -E6, activates IL-6/STAT3 signaling and remodel tumor microenvironment favoring the development of cervical cancer after the elongated latency of the disease." (PMID 26308848, 2015). "Our recent observation demonstrate a strong association of elevated miR-21 expression with active STAT3 and an inverse correlation with level of Let-7a in tumor tissues from cervical cancer lesions (unpublished data)." (PMID 25539644, 2014). "GRIM-19 was originally identified as a tumor-suppressive protein that was involved in cell death through the association and suppression of STAT3; Its expression is down regulated in renal, prostate and cervical cancers." (PMID 21765936, 2011).
cervical carcinoma (continued). "We have shown in our previous publication that GRIM-19 loss correlates with a high STAT3 activity in primary cervical cancers." (PMID 21765936, 2011). "Inflammatory cytokine IL-6, a potent inducer of STAT3 activity through binding to gp130 associated receptors and Jak/Tyk kinases, has received particular attention in the pathogenesis of cervical cancer." (PMID 20977777, 2010). "Except for Mcl-1 expression in cervical carcinomas, the expressions of these genes are associated with elevated p-Stat3 (Tyr705) with statistic significance (P<0.05)." (PMID 17311011, 2007). "Therefore, our study strongly reported that tumor progression is associated with the high expression of M2-TAM and STAT3/NF-κB pathways, leading to lower survival in cervical cancer." (PMID 39061137, 2024). "In addition, STAT3 expression was associated with inflammation and tumor progression in cervical cancer." (PMID 38065854, 2023). "The expression level of these hypoxia-related genes was significantly associated with the prognosis of cervical cancer patients and could be controlled by SD-36, a STAT3 degrader." (PMID 36551576, 2022). "hypothesized that in cervical cancer cells there is a strong correlation between lower let-7a expression and increased expression and activation of STAT3, in high-risk HPV-16 infection with higher levels of E6 oncoprotein." (PMID 35164678, 2022). "There is a strong association between HPV infection and STAT-3 overexpression in cervical cancer." (PMID 33671013, 2021). "To further investigate the mechanism underlying aberrant miR‐223 expression in cervical cancer cells, we first analyzed the sequence of the miR‐223 promoter by using jaspar software and found two conserved binding sites of STAT3 in the distal promoter of the miR‐223 gene." (PMID 32491253, 2020). "Also, TMS-TMF-4f suppressed both constitutive and IL-6-inducible levels of phosphorylated STAT3 (p-STAT3) and associated proteins such as Mcl-1, cyclin D1, survivin, and c-Myc in both cervical cancer cells." (PMID 31816985, 2019). "Additionally, autocrine STAT3 activation is an integral part of HPV-mediated cervical cancer, and loss of STAT3 expression is detrimental to high-risk HPV infection of keratinocytes." (PMID 31892232, 2019). "Furthermore, another previous work reported an over-activation of STAT3 observed in tissues from patients with cervical cancer, which is associated with increased induction of anti-apoptotic genes such as Bcl-xl, survivin and Mcl-I." (PMID 26346346, 2015). "Further, blocking of oncogenic E6 gene expression in cervical cancer cells by E6-specific siRNA resulted in an increase in level of Let-7a and corresponding decline in miR-21 which was accompanied by loss of active STAT3 and increase in PTEN in E6-transfected SiHa cells." (PMID 25539644, 2014). "A genetic analysis of cervical cancer tumor tissue was conducted to assess the expression of STAT3, Snail, PD‐1, HPV16, HPV18, FOXP3, EXPORTIN 5 (XPO5), CXCR4, CXCL12, and CD8." (PMID 41263059, 2025). "In cervical cancer, Cry1 regulates chemoresistance by inhibiting apoptosis through the STAT3 pathway." (PMID 41142939, 2025). "Information is available on the effect of STAT3 expression on the presence and characteristics of stem cells in cervical cancer." (PMID 40729003, 2025). "Protein expressions of STAT3, NF‐κB, CD163, and CD204 in cervical cancer and the correlation of association between them." (PMID 41263059, 2025). "This study identified natural compounds from C. lanceolatus that inhibit STAT3, demonstrating suppressive effects on cervical cancer cell lines and highlighting their anticancer properties." (PMID 40061959, 2025).
cervical carcinoma (continued). "Recent studies examining the pathogenic mechanisms underlying cervical cancer have focused on the Wnt, Notch, BMP, and Jak-Stat3 signaling pathways." (PMID 40297811, 2025). "The STAT3 pathway has been identified as a potential target for many cancers, including cervical cancer, lymphomas, hepatocellular carcinoma, multiple myeloma tumours, and leukemia." (PMID 40061959, 2025). "Previous studies have shown that activation of the IL-6 signaling axis induces the autocrine and paracrine phosphorylation of STAT3 in HPV-positive cervical cancer cells, where this pathway is crucial for cancer cell proliferation and survival." (PMID 40143240, 2025). "STAT3 knockdown dramatically enhanced the level of autophagy and decreased the survival of cervical cancer cells." (PMID 39744564, 2025). "Our results support the idea of the usefulness of the chemosensitisation of cancer cells using molecular targeting, especially in reference to the connection between STAT3/NANOG activation in the cervical cancer HeLa cell model." (PMID 40729003, 2025). "STAT3 together with IL-6 can also lead to activation of epithelial to mesenchymal transition in BC and cervical carcinoma." (PMID 38892394, 2024). "Cervical cancer cells have been found to have high levels of STAT3 expression, and small molecule inhibition of STAT has been shown to facilitate cervical cancer cell death in vitro." (PMID 38474047, 2024). "Another study indicated that SNHG12 plays a significant regulatory role in the progression of cervical cancer by modulating the miR-125b/STAT3 axis." (PMID 38566229, 2024). "STAT3 is considered an oncogenic gene or RNA transcription activator in various human cancers, such as cervical cancer, BC, and oral squamous cell carcinoma." (PMID 38172648, 2024). "STAT3, AP-1, and NF-κB are critical oncogenic transcription factors that play a crucial role in the carcinogenesis of various cancer cells, including cervical cancer." (PMID 39273231, 2024). "Then, we tested the direct regulation of JAK1 and STAT3 exerted by miR-30a and miR-34c, respectively, and validated its effect on the proliferation rates of the cervical cancer cell lines." (PMID 38891028, 2024). "Evidence confirmed that LINC00240 can enhance cervical cancer progression by inducing miR-124-3p/STAT3/MICA-mediated natural killer T (NKT) cell tolerance." (PMID 39595204, 2024). "The association correlation between the expression of CD204+ and CD163+ M2-TAM with STAT3/NF-κB signaling pathways in the tumor microenvironment (TME) was studied in 691 patients with cervical cancer." (PMID 39061137, 2024). "Previous data from our group had shown that IL6R, JAK1/JAK2, and STAT3/STAT5b were dysregulated in locally advanced cervical cancer." (PMID 38891028, 2024). "We validated the interactions of miR-30a and miR-34c with JAK1 and STAT3, respectively, through dual-luciferase and expression assays in cervical carcinoma-derived cell lines." (PMID 38891028, 2024). "CAF-CM increased the phosphorylation levels of Jak-2 and Stat3 in cervical cancer cell lines, however, treatment with anlotinib attenuated this promotion." (PMID 39193386, 2024). "This was also observed for cervical cancer cells upon silencing of ITGB6 through inactivation of the JAK/STAT3 signaling pathway." (PMID 38890650, 2024). "Study have showed that BCL3 was high expression in esophageal squamous cell carcinoma and exerted an oncogenic function by regulating STAT3 in human cervical cancer." (PMID 38767825, 2024). "STAT3/Akt is a key pathway regulating tumor progression and is closely related to the occurrence of many tumors, such as neuroblastoma and cervical cancer." (PMID 38468814, 2024). "And anlotinib not only inhibited the secretion of pro-cancer cytokines induced by CAFs, but also inhibited the phosphorylation of Jak2 and Stat3 in cervical cancer cells induced by CAFs." (PMID 39193386, 2024).
cervical carcinoma (continued). "The cytotoxic activity of NKT cells is facilitated by the LINC00240/miR124-3p/STAT3/MICA axis in cervical cancer." (PMID 37784183, 2023). "Bladder cancer-associated (BLCAP) inhibited STAT3 phosphorylation, whereas A-to-I RNA editing by ADAR1 suppressed this inhibition to STAT3 activation in cervical cancer cell lines, thus driving the progression of cervical carcinogenesis." (PMID 37612540, 2023). "The STAT3 signaling pathway induces the VEGF by stimulating IL-6 in C22A cervical carcinoma cell lines." (PMID 36865747, 2023). "For this reason, a large number of studies analyze the molecular mechanisms to inhibit STAT3 to use them as therapeutic targets in cervical cancer." (PMID 37372319, 2023). "NKT cell tolerance and cervical cancer progression is greatly promoted by LINC00240 regulation of STAT3 and MICA." (PMID 37346034, 2023). "The expression of STAT3 in cervical cancer has acquired great relevance due to various reports that associate its activity with the malignancy grade of cervical lesions." (PMID 37372319, 2023). "Patients with cervical cancer with high SERPINB3/SCCA expression had increased expression of phosphorylated STAT3 (p-STAT3) and CD11b." (PMID 37279067, 2023). "The positive feedback loop of exosomal MALAT1/miR-370-3p/STAT3 mediates the cisplatin resistance of cervical cancer cells affecting PI3K/Akt pathway." (PMID 36793374, 2023). "Subsequently, a network pharmacology analysis, which focused on target genes, identified STAT3 as a key therapeutic target for cervical cancer." (PMID 38004443, 2023). "For example, the STAT3 nucleotide inhibitor AZD9150 has demonstrated some oncogenic effects in lung and lymphoma patients, and BBI608, a STAT3 inhibitor, can inhibit the proliferation of cervical cancer primary cells in patients." (PMID 37173892, 2023). "PGG suppresses the STAT3 expression and activation in various cancer cells, including prostate, breast, head and neck, and cervical cancer cells." (PMID 37375411, 2023). "In CC, lncRNA MALAT1 attenuates cisplatin-induced apoptosis of cervical cancer cells by regulating the STAT3 signal through miR-21." (PMID 36793374, 2023). "Next, this study verified that STAT3 promotes the proliferation, metastasis, clone formation and subcutaneous tumorigenesis of cervical cancer cells in vivo and in vitro." (PMID 35057825, 2022). "CD109 is drastically expressed in cervical cancer and upregulates epidermal growth factor receptor (EGFR)-mediated STAT3 phosphorylation, enabling cervical cancer cell migration and proliferation, and supporting cancer cell phenotype." (PMID 35508982, 2022). "The activation of STAT3 determines the sensitivity of cervical cancer cells to TRAIL-induced apoptosis and can be abrogated by inhibiting the Janus kinase 2 (JAK2), which phosphorylates STAT3." (PMID 36145459, 2022). "STAT3, one of the targets of miR-125a, suppressed tumor invasion as well as metastasis in cervical carcinoma." (PMID 35955794, 2022). "Overall, the scientific data show that resveratrol has the ability to target/inhibit certain signaling molecules (EGFR, VEGFR, PKC, JNK, ERK, NF-kB, and STAT3) involved in cervical cancer cell proliferation and survival." (PMID 36558430, 2022). "IL-6 phosphorylates STAT3 and induces STAT3 to promote the invasion of cervical cancer cells by activating the transcription of matrix metalloproteinase (MMPs)." (PMID 35645817, 2022). "In short, STAT3 not only promotes the abilities of proliferation and migration in cervical cancer cells, but also restrain the autophagy of cervical cancer." (PMID 35057825, 2022). "According to our findings, after impeding genic STAT3, the productivity and metastasis of cervical cancer cells decreased, while the autophagy increased." (PMID 35057825, 2022).